MIR3115 (microRNA 3115)
Synonyms: hsa-mir-3115; mir-3115
Gene: MicroRNA gene on chromosome 1 (23,044,305 to 23,044,372, forward strand). Ensembl gene ENSG00000263793.
Homologues: Orthologues: chimpanzee MIR3115 (100% identical), pig MIR3115 (100% identical).